KCNA1 (potassium voltage-gated channel subfamily A member 1)
Diseases named in the same sentence as KCNA1 in open-access papers (continued):
Sharing a sentence is not in itself a finding about the gene and the disease.
cervical cancer (3 papers, 2019 to 2024). A primary or metastatic malignant neoplasm involving the cervix. "In the present study, we revealed the relationship between KCNA1 and cervical cancer, and explored the underlying mechanisms to provide a theoretical basis for the discovery of new clinical treatments against cervical cancer." (PMID 31354026, 2019). "Therefore, our study suggests that KCNA1 might be utilized as a potential and novel diagnostic and therapeutic target for cervical cancer." (PMID 31354026, 2019). "This study aimed to identify the role of KCNA1 in cervical cancer and explore the related mechanism." (PMID 31354026, 2019). "To further investigate the function of KCNA1 in regulating the biological function of cervical cancer cells, we examined proliferation, migration, and invasion in the previous established stable KCNA1 knockdown and overexpression HeLa cells." (PMID 31354026, 2019). "Taken together, we demonstrated that KCNA1 was significantly upregulated in cervical cancer tissues and cell lines, and correlated with poor prognosis." (PMID 31354026, 2019). "To identify the role of KCNA1 in cervical cancer, we first examined the expression of KCNA1 in cervical cancer tissues from 20 patients." (PMID 31354026, 2019). "The present study has demonstrated that KCNA1 is an oncogene excessively expressed in cervical cancer, and promotes tumor progression by regulating the Hhg, Wnt and Notch signaling pathways and the mitochondrial capacity." (PMID 31354026, 2019). "The levels of KCNA1 in cervical cancer tissues and cell lines were examined by Western blot and qPCR." (PMID 31354026, 2019). "To further confirm these results, we detected protein levels of KCNA1 in cervical cancer cell lines (HeLa, SiHa, and C-33 A) and normal cervical epithelial cell line Ect1/E6E7 by Western blot." (PMID 31354026, 2019). "The observation that KCNA1 is upregulated in cervical cancer tissues is more likely to trigger an oncogenic state, rather than simply be the result of a compensatory mechanism to maintain cellular homeostasis." (PMID 31354026, 2019). "KCNA1 affects the growth, migration and infiltration of cervical cancer cells and affects cell proliferation-related signaling pathways." (PMID 31354026, 2019). "Our results indicated that the three different cervical cancer cell lines showed significantly higher expression of KCNA1 than human normal cervical cell lines (p < 0.01)." (PMID 31354026, 2019). "KCNA1 was highly expressed in cervical cancer tissues and cell lines, and correlated with poor prognosis." (PMID 31354026, 2019). "In conclusion, we have found that KCNA1 is highly expressed in tumor tissues of cervical cancer patients." (PMID 31354026, 2019). "Hence, the assessment of KCNA1 expression levels in cervical cancer can serve as a prognostic indicator for tumor stages and patient survival durations." (PMID 39337406, 2024). "Taken together, our data indicated that KCNA1 regulated cervical cancer development in vivo." (PMID 31354026, 2019). "To identify whether KCNA1 affected cervical cancer cell growth, we first generated stable KCNA1 knockdown and overexpression HeLa cell lines by lentivirus." (PMID 31354026, 2019). "In addition, qPCR analysis indicated that the mRNA levels of KCNA1 were higher (ratio >2) in 17/20 representative cervical cancer patient tissues." (PMID 31354026, 2019). "In our study, we demonstrated a tumor promoting role of KCNA1 in cervical cancer." (PMID 31354026, 2019). "In addition, KCNA1 may possibly contribute to the process of programmed cell death in cervical cancer cells." (PMID 39337406, 2024). "Therefore, our results suggested that KCNA1 might affect the cellular function of cervical cancer cells by regulating the Hhg, Wnt and Notch signaling pathways." (PMID 31354026, 2019). "Therefore, detecting the expression levels of KCNA1 in cervical cancer could be used to predict tumor stages and survival time for patients." (PMID 31354026, 2019).
cervical cancer (continued). "Therefore, our data suggested that KCNA1 regulated growth of cervical cancer cells." (PMID 31354026, 2019). "Furthermore, KCNA1 might also function on cell apoptosis in cervical cancer." (PMID 31354026, 2019). "However, currently there has been no study focusing on the function of KCNA1 in cervical cancer." (PMID 31354026, 2019).
developmental and epileptic encephalopathy (3 papers, 2021 to 2022). An epilepsy associated with developmental impairment that may be due to either the underlying etiology or the superimposed epileptic activity, or both. "Our survival analysis indicated SUDEP first occurred after two months of age in both male and female mutants, which is four to six weeks later than common monogenic developmental epileptic encephalopathy SUDEP models, such as Scn1a, Scn8a and Kcna1 mutants." (PMID 34396109, 2021).
Dystonia (3 papers, 2020 to 2023). An abnormally increased muscular tone that causes fixed abnormal postures. "Importantly, the phenotypes associated with mutations in the DYT genes enriched in the putamen ‘cyan’ module belonged to different clinical subtypes of dystonia, namely isolated dystonia (ANO3 and HPCA), combined dystonia (KCTD17 and ADCY5), and paroxysmal dystonia (KCNA1, CACNA1A, PRRT2 and SCN8A)." (PMID 32889528, 2020).
glioblastoma (3 papers, 2020 to 2024). The most malignant astrocytic tumor (WHO grade IV). "The Ivy Glioblastoma Atlas Project suggests that high KCNA1 expression may be associated with glioblastoma progression." (PMID 38172959, 2024). "In this study, we validated that KCNA1 promotes cell growth and invasion of glioblastoma cells both in vivo and in vitro." (PMID 38172959, 2024). "To further determine the specific mechanisms by which KCNA1 influences glioblastoma progression, we conducted RNA sequencing in the NC and sh-KCNA1 groups." (PMID 38172959, 2024). "In order to gain further insights into the role of KCNA1 in ferroptosis, we induced ferroptosis in glioblastoma cells using the drug Erastin." (PMID 38172959, 2024). "However, recent research on glioblastoma indicated that KCNA1 promotes the invasion of tumor cells in highly infiltrative and invasive cell population at the tumor edge." (PMID 38172959, 2024). "Additionally, we demonstrated for the first time that KCNA1 inhibits ferroptosis in glioblastoma by positively regulating the expression of SLC7A11." (PMID 38172959, 2024). "Therefore, this study aimed to propose a new mechanism by which KCNA1 regulates the expression of SLC7A11 in glioblastoma." (PMID 38172959, 2024). "Moreover, KCNA1 was upregulated during seizures and tumor formation in glioblastoma models." (PMID 38172959, 2024). "We found KCNA1 is overexpressed in GBMiinv cells in vivo in patient-derived orthotopic xenograft (PDOX) models and in patient glioblastoma tumor, functioning as a downstream target of microRNAs in GBM cells to promote tumor invasion and metastasis." (PMID 38172959, 2024). "In vivo, we implanted stable transfections of negative control virus (NC) and KCNA1-interfering lentivirus (shKCNA1) U87 cells into the mouse brains to simulate the growth of glioblastoma." (PMID 38172959, 2024).
myoclonic epilepsy (3 papers, 2015 to 2022). A group of epilepsy syndromes in which myoclonic seizures are a prominent feature. "Of note, a de novo copy number variation in KCNA1 extending from the PVP motif to the end of the S6 helix has been identified in a 3-year-old proband with serious myoclonic epilepsy in infancy who died of SUDEP." (PMID 35897654, 2022).
Nystagmus (3 papers, 2021 to 2023). Rhythmic, involuntary oscillations of one or both eyes related to abnormality in fixation, conjugate gaze, or vestibular mechanisms. "Two of the four nystagmus variants map to S4 but the small total number of KCNA1 variants associated with nystagmus limits the reliability of drawing any conclusions about a potential location bias." (PMID 37240170, 2023). "Until recently, only two KCNA1 variants had ever been linked to nystagmus, F184C and F303V." (PMID 37240170, 2023). "In addition, we explore emerging links between KCNA1 and musculoskeletal abnormalities and nystagmus that are being revealed by recently described mutations." (PMID 37240170, 2023). "Moreover, the recently identified variants highlight emerging links between KCNA1 and musculoskeletal abnormalities and nystagmus, conditions not typically associated with KCNA1." (PMID 37240170, 2023).
paroxysmal dyskinesia (3 papers, 2020 to 2022). Paroxysmal dyskinesia (PD) is a rare heterogenous group of movement disorders manifesting as abnormal involuntary movements that recur episodically and last only a brief time. "KCNA1 mutations can also cause hypomagnesemia and paroxysmal dyskinesia in rare cases." (PMID 32316562, 2020).
schizophrenia (3 papers, 2022 to 2023). A major psychotic disorder characterized by abnormalities in the perception or expression of reality. "In this study, we found a strong association between the KCNIP4 gene and adverse reactions during aripiprazole treatment in schizophrenia patients, while KCNA1/Kv1.1 also showed a significant association (rs57468930, P = 1.56 × 10−6)." (PMID 37491364, 2023).
status epilepticus (3 papers, 2018 to 2020). Status epilepticus is defined as a continuous seizure lasting more than 30 min, or two or more seizures without full recovery of consciousness between any of them. "Notably, KCNA1 is the target of Isoflurane, a commonly used inhalation agent, which has anticonvulsant properties and can terminate refractory status epilepticus in patients." (PMID 33569037, 2020).
Tremor (3 papers, 2018 to 2021). An unintentional, oscillating to-and-fro muscle movement about a joint axis. "For example, mutations in the Shaker-like voltage-gated potassium channel Kv1.1 (KCNA1) are known to cause tremor and temporal lobe epilepsy." (PMID 33479380, 2021).
Ventricular arrhythmia (3 papers, 2019 to 2021). "Since the ventricles can be a source of lethal arrhythmias and Kcna1–/– mice exhibit seizure-related sudden death, determining the effects of Kv1.1 mutations on ventricular arrhythmia susceptibility is especially important." (PMID 31250689, 2019).
autism (2 papers, 2021 to 2024). Persistent deficits in social interaction and communication and interaction as well as a markedly restricted repertoire of activity and interest as well as repetitive patterns of behavior. "In addition to the repetitive and social behavioral abnormalities identified in this work, Kcna1 mutant mice exhibit several other characteristics observed in ASD, suggesting that Kv1.1 subunits contribute to networks or pathways underlying autism." (PMID 33484493, 2021).
Dravet syndrome (2 papers, 2017 to 2024). "On the other hand, the ketogenic diet is one of the most effective treatments for Dravet syndrome and has clear protective effects in animal models that lack Scn1a/scn1Lab and Kcna1." (PMID 37594756, 2024). "While there are still little data about impairments of brain metabolism, the studies revealed ketogenic diets to be mostly effective, particularly for Dravet syndrome with identified SCN1A mutations as well as mouse and zebrafish models with SCN1A and KCNA1 mutations." (PMID 37594756, 2024).
early-onset epileptic encephalopathy (2 papers, 2020 to 2021). "Variants affecting prolines in the PVP motif and in closely related residues have been identified in KCNA2- and recently in KCNA1-associated early-onset epileptic encephalopathy." (PMID 33802230, 2021).
focal epilepsy (2 papers, 2019 to 2024). A seizure caused by a localized disorder. "Mutations in the KCNA1 (KV1.1) significantly reduce the amplitude of K+ currents by impacting the IK currents, thereby increasing excitability and are linked to partial epilepsy." (PMID 39375030, 2024).
migraine (2 papers, 2014 to 2021). "In this study, we now describe a 31-year-old man carrying a dominant-negative, loss-of-function mutation in KCNA1 who displays a new phenotype characterized by episodes of hyperthermia, short-sleep duration, and severe migraine." (PMID 25642194, 2014). "Nevertheless, the presence of long-lasting episodes of severe migraine characterized by nausea, photo- and phonophobia, occurring independently of attacks of EA1, also demonstrate that our probands's symptoms do not fall within the spectrum previously reported for KCNA1 mutations." (PMID 25642194, 2014).
paroxysmal kinesigenic dyskinesia (2 papers, 2020 to 2021). "In our case series, we present two individuals with PxD including one with classical paroxysmal kinesigenic dyskinesia, who carry new likely pathogenic de novo variants in KCNA1 (p.Gly396Val and p.Gly396Arg)." (PMID 34305802, 2021). "Two KCNA1 mutations have been associated with paroxysmal kinesigenic dyskinesia (PKD), another type of paroxysmal movement disorder along with EA." (PMID 32316562, 2020).
generalized tonic-clonic seizures (1 paper, 2020). "To investigate the ability of Kcna1-dCas9 to treat chronic temporal lobe epilepsy we analysed the frequency of generalized tonic-clonic seizures (Racine stage 5) in each animal before and after doxycycline administration using continuous video-EEG recordings." (PMID 32129831, 2020).
medulloblastoma (1 paper, 2017). A malignant, invasive embryonal neoplasm arising from the cerebellum. "Although a smaller set of tumors from the GTML model shows a resemblance to Group 4 medulloblastoma and MYCN-driven postnatal stem cells give rise to tumor cells that are positive for the Group 4 KCNA1 marker, there are as yet no reliable Group 4 models for medulloblastoma." (PMID 28333115, 2017).
megalencephaly (1 paper, 2020). A congenital abnormality in which the occipitofrontal circumference is greater than two standard deviations above the mean for a given age. "Indeed, spontaneous epileptic activity has been reported in both the Kv1.1S309T/+ mice (carrying the missense mutation S309T in the S4 of Kv1.1 channels) and the megalencephaly mice, mceph/mceph (in which a frameshift mutation in the KCNA1 gene leads to a truncated non-functional protein)." (PMID 32331416, 2020).
preeclampsia (1 paper, 2020). Preeclampsia is a hypertensive disorder of pregnancy that is characterized by new-onset hypertension with proteinuria presenting after 20 weeks of gestation, and depending on mild or severe forms may initially present with severe headache, visual disturbances, and hyperreflexia. "The findings demonstrated that miR-125b significantly inhibited KCNA1 in trophoblast cells, and suppressed GPC1 expression in endothelial cells, suggesting KCNA1 and GPC1 may play distinct roles in the pathogenesis of preeclampsia." (PMID 32435510, 2020).
tumor (18 papers, 2014 to 2025). "Western blot analysis was used to validate the increased expression of proteins associated with tumor invasion in KCNA1-OE cells." (PMID 38172959, 2024). "CCK8, colony formation assay, scratch assay, transwell assay, and 3D tumor spheroid invasion assays were to determine how KCNA1 affects the growth and invasion of GBM cells." (PMID 38172959, 2024). "While the expression of most B-cell-related genes is associated with better survival in both PFS and OS, there are some tumor-related genes in which the expression is associated with a decrease in survival, such as LGR5 or KCNA1." (PMID 36012390, 2022). "The result showed that PTGFR had a lower expression level in tumor tissue, yet LILRA2 and KCNA1 were highly expressed in tumor tissue." (PMID 36091124, 2022). "In the present study, we found that KCNA1 was highly expressed in cervical cancer tumor tissues compared with adjacent non-tumor tissues." (PMID 31354026, 2019). "In addition to carrying the Braf gene, chromosome 6 carries several genes that are highly expressed in the LNM and tumor populations (Aqp1, Col1a2, Cav1, Cav2, Ptn, RaRes2, Fkbp9, Actg2, Ybx3, Mgp, Sox5, Kcna1, and Ptms)." (PMID 40571713, 2025). "Therefore, our experiments elucidated the role of KCNA1 in inhibiting ferroptosis and consequently promoting tumor growth." (PMID 38172959, 2024). "Finally, we validated in vivo that the inhibition of KCNA1 in cells led to tumor suppression during intracranial growth, extended survival time in mice, and reduced the expression of SLC7A11." (PMID 38172959, 2024). "Furthermore, our research indicates that KCNA1 promotes tumor progression by inhibiting ferroptosis, which is consistent with the conclusion of other studies that ferroptosis is suppressed during cell growth and invasion." (PMID 38172959, 2024). "Summarily, KCNA1 is highly expressed at the tumor leading edge and may be related to the mitochondria in GBM cells." (PMID 38172959, 2024). "KCNA1 was reported to modulate the invasiveness in tumor cells." (PMID 32435510, 2020). "Moreover, our in vivo nude mouse tumor formation experiments further indicated that KCNA1 knockdown HeLa cells generated smaller tumors than control cells, whereas KCNA1 overexpressing HeLa cells formed larger tumors." (PMID 31354026, 2019). "Compared with adjacent non-tumor tissues, KCNA1 was significantly upregulated in tumor tissues." (PMID 31354026, 2019). "Therefore, our research suggests that KCNA1 may promote tumor growth and invasion by upregulating the expression of SLC7A11 and inhibiting ferroptosis, making it a promising therapeutic target for GBM." (PMID 38172959, 2024). "Besides, DNA methyl transferases and polycomb repressive complexes could decrease the expression of tumor-suppressive genes, including KCNA1, which might sustain the cancer inhibitory effects of KCNA1." (PMID 31354026, 2019). "Most of the genes were down-regulated in tumor tissues, for example, EDN3, KCNA1, TFAP2B, and ANK3 genes were significantly down-regulated in KICH, COAD, HNSC, KIRC, THCA, and KIRP." (PMID 41174507, 2025). "The tumours from which the cell lines were derived have been assigned to MB molecular subtypes using IHC for β-catenin, Gli1, NPR3 and KCNA1, and sequencing of the β-catenin gene (CTNNB1)." (PMID 24887326, 2014). "Our study has shown that KCNA1 rescues GBM cells from ferroptosis and promoting tumor progression." (PMID 38172959, 2024). "We first observed increased expression of KCNA1 in tumor tissues compared with adjacent non-tumor tissues." (PMID 31354026, 2019).
cancer (13 papers, 2008 to 2025). A tumor composed of atypical neoplastic, often pleomorphic cells that invade other tissues. "The mutation rates of different MHGs varied widely across cancer tissues, with ANK3 having the highest mutation rate (47%), followed by KEL (18%), TRPM7 (16%), KCNA1 (13%), CNNM2 (9%), CNNM1 (9%), TFAP2B (9%), CNNM4 (9%), XK (7%), and EDN3 (5%)." (PMID 41174507, 2025). "Six genes were found to be implicated in cancer etiology/progression/clinical outcomes with high degree of certainty: MMP1, DDX4, TRPM3, DPP6, KCNA1, and MUC17." (PMID 32625238, 2020). "However, significantly higher levels of KCNA1 mRNA have been observed in cancer cells compared to healthy tissue, with the highest expression of this gene found in HeLa cells." (PMID 40361464, 2025). "Monitoring KCNA1 expression levels might serve as a marker for evaluating cancer progression and estimating survival outcomes." (PMID 40361464, 2025). "EDN3, TFAB2B showed high levels of methylation in almost all cancers, while CNNM1, CNNM2 and KCNA1 showed high levels of methylation in at least half (7 or more) of the cancers." (PMID 41174507, 2025). "We evaluated the overall genetic alterations in all KCNA genes (KCNA1, KCNA2, KCNA3, KCNA4, KCNA5, KCNA6, KCNA7, KCNA10) using the TCGA Pan-Cancer Atlas dataset, collecting data from 32 human cancers (10,953 patients in total)." (PMID 36978819, 2023).
neurological disease (11 papers, 2016 to 2026). "This gap is essential to explore because the mammalian homolog Kv1.1 (KCNA1) is expressed in both the brain and the heart, and its dysfunction has been linked to neurological diseases and autonomic cardiac abnormalities." (PMID 41548155, 2026).